OOEP (oocyte expressed protein)
Description:
Component of the subcortical maternal complex (SCMC), a multiprotein complex that plays a key role in early embryonic development. The SCMC complex is a structural constituent of cytoplasmic lattices, which consist in fibrous structures found in the cytoplasm of oocytes and preimplantation embryos. They are required to store maternal proteins critical for embryonic development, such as proteins that control epigenetic reprogramming of the preimplantation embryo, and prevent their degradation or activation. As part of the OOEP-KHDC3 scaffold, recruits BLM and TRIM25 to DNA replication forks, thereby promoting the ubiquitination of BLM by TRIM25, enhancing BLM retainment at replication forks and therefore promoting stalled replication fork restart. Positively regulates the homologous recombination-mediated DNA double-strand break (DSB) repair pathway by regulating ATM activation and RAD51 recruitment to DSBs in oocytes. Thereby contributes to oocyte survival and the resumption and completion of meiosis.
Synonyms: hOEP19; C6orf156; KHDC2; Em:AC019205.2; FLOPED
Tractability: No criterion of Open Targets' tractability assessment is met for any kind of drug.
Gene: Protein-coding gene on chromosome 6 (73,368,555 to 73,395,133, reverse strand). Ensembl gene ENSG00000203907.
Subcellular location: Cytoplasm; Nucleus
Gene Ontology:
Molecular function: protein binding; RNA binding; structural constituent of cytoplasmic lattice
Biological process: actin filament organization; embryonic pattern specification; establishment of spindle localization; establishment or maintenance of apical/basal cell polarity; positive regulation of double-strand break repair; positive regulation of double-strand break repair via homologous recombination; positive regulation of embryonic development; positive regulation of meiotic nuclear division; protein storage; regulation of cell division; regulation of establishment of protein localization; regulation of protein localization; replication fork processing
Cellular component: cytoplasm; nucleus; protein-containing complex; subcortical maternal complex; cell cortex; cytoplasmic lattice
Genetic constraint (gnomAD): Loss-of-function variants: 14 observed, 13.26 expected, observed/expected ratio (o/e) 1.06, 90% interval 0.69 to 1.63. The upper end of that interval is the gene's LOEUF score, 1.63, which puts it in group 6 of 6, group 1 being the genes least tolerant of losing a copy. Missense variants: 168 observed, 172.47 expected, observed/expected ratio (o/e) 0.97, 90% interval 0.86 to 1.11. Synonymous variants: 76 observed, 71.22 expected, observed/expected ratio (o/e) 1.07, 90% interval 0.89 to 1.29.
Homologues: Orthologues: chimpanzee OOEP (99% identical), macaque OOEP (95% identical), pig OOEP (61% identical), dog OOEP (50% identical), mouse Ooep (42% identical), rat Ooep (41% identical). Paralogues in human: KHDC3L (26% identical).
Diseases named in the same sentence as OOEP in open-access papers:
OOEP is named in the same sentence as 5 diseases in open-access papers, as found by Europe PMC text mining. Sharing a sentence is not in itself a finding about the gene and the disease. The quoted sentences say what the papers report.
female infertility (1 paper, 2022). Diminished or absent ability of a female to achieve conception. "Collectively, these results indicate that biallelic mutations in OOEP and NLRP5 may be a potential genetic cause of female infertility." (PMID 35946397, 2022). "Mutations in OOEP and ZBED3, components of the SCMC, have not previously been associated with human female infertility." (PMID 35946397, 2022).
Infertility (1 paper, 2022). "Since it is unknown whether mutations of OOEP are associated with human infertility, wild‐type and mutant OOEP vectors were transfected into HEK 293T cells to evaluate the functional effects of the identified OOEP mutations in vitro." (PMID 35946397, 2022).
male infertility (1 paper, 2023). The inability of the male to effect fertilization of an ovum after a specified period of unprotected intercourse. "It demonstrated the co-expression of OOEP with genes related to human reproduction, spermatogenesis, male infertility, and located in the Y chromosome." (PMID 36999055, 2023). "Although no obvious association of OOEP with male reproduction the co-expression network performed for OOEP demonstrated the co-expression with genes located in the Y chromosome, related to human reproduction, spermatogenesis, and male infertility." (PMID 36999055, 2023).
ovarian failure (1 paper, 2018). "Thus, OOEP may participate in the regulation of genome stability in oocytes and contribute to ovarian failure and reproductive aging under physiological or pathological conditions." (PMID 29955025, 2018).
teratozoospermia (1 paper, 2023). "Except for OOEP, all the other downregulated genes have been linked to male infertility disorders, including NOA and teratozoospermia." (PMID 36999055, 2023). "Since co-expressed genes are simultaneously active, downregulation of OOEP in patients with NOA and teratozoospermia could affect the entire gene expression regulation, even though the structure or even the protein expression might not be affected." (PMID 36999055, 2023). "In NOA and teratozoospermia, 145 meiosis-related genes were differentially expressed in comparison to the control, including OOEP; despite no recognized role in male reproduction, OOEP was co-expressed with genes related to male fertility." (PMID 36999055, 2023).